LUC7L3 (LUC7 like 3 pre-mRNA splicing factor)
Description:
Binds cAMP regulatory element DNA sequence. May play a role in RNA splicing.
Synonyms: CREAP-1; CROP; LUC7A; OA48-18; FLJ11063; CRA; hLuc7A
Tractability: PROTAC: UniProt records ubiquitination sites on it; ubiquitination databases record sites on it; its protein half-life has been measured.
Gene: Protein-coding gene on chromosome 17 (50,719,565 to 50,756,219, forward strand). Ensembl gene ENSG00000108848.
Subcellular location: Nucleus speckle
Subcellular location (Human Protein Atlas): Nuclear speckles
Pathways (Reactome):
Metabolism of RNA: mRNA Splicing - Major Pathway
Gene Ontology:
Molecular function: mRNA binding; protein binding; RNA binding
Biological process: RNA splicing; mRNA splice site recognition
Cellular component: nuclear speck; nucleus; nucleoplasm; U1 snRNP; U2-type prespliceosome
Genetic constraint (gnomAD): Loss-of-function variants: 6 observed, 53.29 expected, observed/expected ratio (o/e) 0.11, 90% interval 0.061 to 0.22. The upper end of that interval is the gene's LOEUF score, 0.22, which puts it in group 1 of 6, group 1 being the genes least tolerant of losing a copy. Missense variants: 281 observed, 454.18 expected, observed/expected ratio (o/e) 0.62, 90% interval 0.56 to 0.68. Synonymous variants: 123 observed, 150.48 expected, observed/expected ratio (o/e) 0.82, 90% interval 0.7 to 0.95.
Homologues: Orthologues: mouse Luc7l3 (99% identical), chimpanzee LUC7L3 (99% identical), macaque LUC7L3 (99% identical), dog LUC7L3 (98% identical), rabbit LUC7L3 (97% identical), rat Luc7l3-ps2 (97% identical), guinea pig LUC7L3 (95% identical), tropical clawed frog luc7l3 (82% identical), zebrafish luc7l3 (75% identical), Drosophila melanogaster CG3198 (35% identical), Caenorhabditis elegans luc-7L3 (28% identical), Caenorhabditis elegans Y119D3B.12 (26% identical). Paralogues in human: LUC7L2 (34% identical), LUC7L (32% identical).
Diseases named in the same sentence as LUC7L3 in open-access papers:
LUC7L3 is named in the same sentence as 19 diseases in open-access papers, as found by Europe PMC text mining. Sharing a sentence is not in itself a finding about the gene and the disease. The quoted sentences say what the papers report.
heart failure (4 papers, 2022 to 2024). Inability of the heart to pump blood at an adequate rate to meet tissue metabolic requirements. "Hypoxia and angiotensin II signals activate splicing factors like RNA-binding motif protein 25 (RBM25) and LUC7-like 3 pre-mRNA splicing factor (LUC7L3), leading to the production of dysfunctional SCN5a variants associated with heart failure." (PMID 39334823, 2024). "LUC7L3, also known as CROP, encodes a protein that is involved in alternative splicing and is associated with human heart failure." (PMID 37745713, 2023). "Currently, there is limited research on LUC7L3, although it is known that LUC7L3 is upregulated in heart failure." (PMID 38410514, 2024). "Only the fact that LUC7L3 is increased in human heart failure tissues and exacerbates heart failure is known." (PMID 36467412, 2022).
breast carcinoma (2 papers, 2022 to 2024). "The alternate expression of LUC7L3 reverses the regulatory effect of miR-370-5p on the phenotype of breast cancer cells, making it a potential new target for cancer treatment." (PMID 38410514, 2024). "To date, many miR-370-5p-associated regulatory axes have been identified in different cancers, including miR-370-5p/LUC7L3 in breast cancer, miR-370-5p/p21 in lung cancer, and SNHG3/miR-370-5p/EZH1 in colorectal carcinoma." (PMID 35359381, 2022).
carcinoma of the head and neck (1 paper, 2012). "The genes in the signature, LDLRAP1, PHF20, and LUC7L3, are known to be involved in carcinoma of the head and neck, tumour-associated antigens, and/or cellular signalling." (PMID 22986368, 2012).
cardiomyopathies (1 paper, 2015). "Consequently, other RNA-binding proteins such as CELF-3, CELF-5, RBM24, RBM25 and LUC7L3 have been linked to the development of cardiomyopathies." (PMID 26116573, 2015).
colon cancers (1 paper, 2017). "JMJD6 has been reported to be over-expressed in oral, breast, lung, and colon cancers and plays important roles in regulation of transcription through interactions with transcription regulator BRD4, histones, U2AF65, Luc7L3, and SRSF11." (PMID 29176719, 2017).
migraine (1 paper, 2021). "Three of the DE genes were DE after cold pressor test (i.e. C vs D) and were therefore not considered to be migraine genes (LUC7L3, SRC and RPGR)." (PMID 33859262, 2021).
neuroblastoma (1 paper, 2024). Neuroblastoma (NB) is the most common solid, extracranial childhood tumor. "In a previous publication, by mapping the N4BP1-associated proteins using mass spectrometry, LUC7L3 was associated with N4BP1 in neuroblastoma cells (original data obtained from Professor Boes)." (PMID 39491646, 2024).
ovarian carcinoma (1 paper, 2021). A malignant neoplasm originating from the surface ovarian epithelium. "Our splicing regulation network analysis showed some splicing factors might be correlated with prognosis-related AS events, including SPEN, SF3B5, RNPC3, LUC7L3, SRSF11 and PRPF38B, suggesting that these splicing factors could play crucial roles in ovarian cancer development." (PMID 34001978, 2021).
Type 1 Diabetes (1 paper, 2022). "LUC7L3 is a gene associated with Type 1 Diabetes and codes for a protein that localizes with a speckled pattern in the nucleus." (PMID 35546387, 2022).
cancer (7 papers, 2007 to 2024). A tumor composed of atypical neoplastic, often pleomorphic cells that invade other tissues. "For instance, LUC7L3, or cisplatin resistance-associated overexpressed protein (CROP), was found to be significantly lower in NPC samples than in controls and other cancer samples." (PMID 38473280, 2024). "Of the many downregulated spliceosome complex proteins in cancer, we captured the interactions between SNRNP70, SRSF5, DDX17 and LUC7L3 in the largest component of the projected downregulated network." (PMID 34728699, 2021). "In this study, expression of LUC7L3 was found to be significantly lower in NPC samples than in controls and other cancer samples." (PMID 22986368, 2012).
tumor (7 papers, 2012 to 2025). "We found that patients with higher BCLC stage, positive microvascular invasion, lower differentiation, and larger tumor diameters had significantly higher LUC7L3 expression." (PMID 38785515, 2024). "The molecular mechanism of LUC7L3 promoting tumor cell proliferation, the relationship between LUC7L3 and RRM2, and its potential diagnostic and therapeutic value need to be further clarified." (PMID 38785515, 2024). "The knockdown of LUC7L3 significantly inhibited tumor cell growth." (PMID 38785515, 2024). "Seven potential tumor antigens, [SREBF1, LUC7L3, LAMA5, PCGF3, HNRNPH1, KLC4, and OFD1], which were associated with nonsense-mediated mRNA decay factor expression, overall survival, and infiltration of APCs and would thus induce a potent anti-tumor T-cell response." (PMID 39399167, 2024). "We identified LUC7L3 as a potential HCC biomarker, as its expression in tumor tissue was markedly elevated, and significantly correlated with worse OS and DFS prognoses." (PMID 38785515, 2024). "In our study, we identified a series of potential tumor antigens, including SREBF1, LUC7L3, LAMA5, PCGF3, HNRNPH1, KLC4, and OFD1, by systematically analyzing alternative splicing and mutation of genes in patients with HNSCC." (PMID 36467412, 2022). "In addition, survival-related AS events might be involved in tumor-related pathways including base excision repair and pyrimidine metabolism pathways, and some splicing factors might be correlated with prognosis-related AS events, including SPEN, SF3B5, RNPC3, LUC7L3, SRSF11 and PRPF38B." (PMID 34001978, 2021).
LUC7L3 also shares sentences with these, for which no sentence is quoted: Alzheimer disease (1 paper); colorectal carcinoma (1); hepatocellular carcinoma (1); infection (1); lung carcinoma (1); Parkinson's (1); respiratory failure (1); translocation renal cell carcinoma (1).